LINC02167 (long independently transcribed non-coding RNA 2167)
Synonyms: FLJ26245
Gene: Long non-coding RNA gene on chromosome 16 (35,743,268 to 35,756,515, forward strand). Ensembl gene ENSG00000261122.
Diseases named in the same sentence as LINC02167 in open-access papers:
LINC02167 is named in the same sentence as 1 disease in open-access papers, as found by Europe PMC text mining. Sharing a sentence is not in itself a finding about the gene and the disease. The quoted sentences say what the papers report.
cancer (1 paper, 2025). A tumor composed of atypical neoplastic, often pleomorphic cells that invade other tissues. "KEGG classification annotation results indicated that the differentially expressed genes were enriched in several cancer-related signaling pathways, such as MAPK, PI3K/AKT, and Wnt, suggesting that LINC02167 may promote CRC metastasis by regulating these cancer pathways." (PMID 40234937, 2025).